NMNAT2 (nicotinamide nucleotide adenylyltransferase 2)
Diseases named in the same sentence as NMNAT2 in open-access papers (continued):
Sharing a sentence is not in itself a finding about the gene and the disease.
ovarian carcinoma (8 papers, 2014 to 2025). A malignant neoplasm originating from the surface ovarian epithelium. "Moreover, high NMNAT2 expression is associated with higher tumor grades and is linked to poorer progression-free survival in ovarian cancers." (PMID 39272943, 2024). "Besides, A study found that depletion of NMNAT-2 led to increased polysome association, enhanced translation of specific mRNAs, and decreased ovarian cancer growth." (PMID 36845744, 2023). "The elevated levels of NMNAT2 in ovarian cancer cells have been shown to decrease the accumulation of toxic proteins through the NMNAT2-NAD+-PARP16 pathway, which then supports cancer cell proliferation." (PMID 39272943, 2024). "Many ovarian cancer cell lines have shown overexpression of NMNAT2, indicating an increase in cytosolic NAD+ levels as well as cell growth." (PMID 39272943, 2024). "Ovarian cancer was also shown to markedly upregulate NMNAT2 expression to enhance NAD+ formation and thereby promote the NAD+-dependent mono ADP-ribosylation (MAR) of ribosomal proteins through the catalytic activity of PARP-16." (PMID 38396769, 2024). "During the submission of this manuscript, two groups reported the distinct roles of NMNAT1 and NMNAT2 in acute myeloid leukemia and ovarian cancer respectively." (PMID 34919052, 2021). "In ovarian cancers, nicotinamide mononucleotide adenylyl transferase 2 (NMNAT2), which mediates the synthesis of NAD+ is highly upregulated." (PMID 35004688, 2021). "There is a significant positive correlation between NMNAT-2 and MARylation levels in the samples of ovarian cancer patients, and a high level of MARylation will lead to poor prognosis with respect to progression free survival." (PMID 35004688, 2021). "Therefore, this study suggested that targeting NMNAT2 using inhibitors could be a promising strategy for treating ovarian cancer." (PMID 38396769, 2024).
polyneuropathy (4 papers, 2021 to 2023). A disease or disorder affecting more than one nerve. "Biallelic loss-of-function (LoF) NMNAT2 mutations are associated with rare, early-onset, or developmental neuropathies, including polyneuropathy and fetal akinesia deformation sequence (FADS) stillbirth." (PMID 34910914, 2021). "The first evidence of humans with mutations in NMNAT2 was found in 2019, with biallelic NMNAT2 loss-of-function mutations found in sisters with polyneuropathy." (PMID 34307460, 2021). "Partial NMNAT2 loss-of-function occurs in an inherited polyneuropathy with neuropathic pain, and NMNAT2 expression level shows wide variation in the human population." (PMID 34595734, 2021). "Human genetic association with NMNAT2 and SARM1 strongly suggests aberrant activation of programmed axon death in polyneuropathies and motor neuron disorders, respectively, and animal studies suggest wider involvement including in chemotherapy-induced and diabetic neuropathies." (PMID 34595734, 2021).
Ataxia (3 papers, 2016 to 2024). Ataxia refers to impaired coordination of voluntary muscle movement. "NMNAT2 cKO mice exhibited evident hindlimb clasping, ataxia and forelimb circling phenotypes (10 out of 10 mice examined), reflecting motor behavioral deficits similar to those observed in many neurodegenerative mouse models." (PMID 37292715, 2023).
cardiac hypertrophy (3 papers, 2018 to 2025). "Therefore, angiotensin II (Ang II) induced cardiac hypertrophy was seen to be reduced when Nmnat2 was overexpressed in mouse models." (PMID 29966233, 2018). "From the data currently available, it would seem that Nmnat2 manipulation, IGF signaling modulation and cellular autophagy targeting may be useful in targeting SIRT6 for future drugs in order to treat cardiac hypertrophy." (PMID 29966233, 2018). "Therefore, it becomes reasonable to conclude that the activation of SIRT6 in Ang-II induced hypertrophy may have been related to Nmnat2 expression and SIRT6, which, in this case, acts as a negative regulator in the case of cardiac hypertrophy." (PMID 29966233, 2018).
Huntington disease (3 papers, 2014 to 2024). Huntington disease (HD) is a rare neurodegenerative disorder of the central nervous system characterized by unwanted choreatic movements, behavioral and psychiatric disturbances and dementia. "mRNA levels of NMNAT2 are significantly reduced in the brains of AD, Parkinson’s disease (PD), and Huntington’s disease (HD) patients." (PMID 37292715, 2023). "Given the role of NMNAT2 in axon survival, the finding that zDHHC17 could regulate NMNAT2 palmitoylation suggests a potential impairment of NMNAT2 palmitoylation and subcellular targeting in Huntington disease models that warrants further investigation." (PMID 25271157, 2014).
non-small cell lung carcinoma (3 papers, 2016 to 2021). A group of at least three distinct histological types of lung cancer, including non-small cell squamous cell carcinoma, adenocarcinoma, and large cell carcinoma. "SIRT3 activates NMNAT2 through deacetylation and increases NAD+ levels in non-small cell lung cancer cells." (PMID 34445574, 2021). "Recent studies also indicated that the function of NMNAT2 is partially overlapped with SIRT3, which improves mitochondrial functions, and is related to energy metabolism in human non-small cell lung carcinoma (NSCLC) cell lines A549." (PMID 27218101, 2016).
bladder cancer (2 papers, 2012 to 2019). "However, the role of NMNAT2 in bladder cancer cells and whether expression of NMNAT2 affects therapeutic efficacy remains unclear." (PMID 31805718, 2019).
dementia (2 papers, 2016 to 2017). Loss of intellectual abilities interfering with an individual's social and occupational functions. "Thus, it is plausible in human that reduced CREB activity results in a decrease in NMNAT2 and synaptic loss, culminating in dementia." (PMID 27254664, 2016).
diabetic neuropathies (2 papers, 2021 to 2024). "In this present study, increased levels of NMNAT2 RNA are directly associated with a decrease in the IENFD from human skin biopsies from patients with diabetic neuropathy, further supporting the role of NMNAT2 in axonal regeneration." (PMID 38256175, 2024).
erythromelalgia (2 papers, 2023 to 2025). A rare neurovascular peripheral pain disorder due to the intermittent blockage of the blood vessels, usually in the lower extremities or hands. "Homozygous partial LOF mutations in NMNAT2 (T94M) were reported in two siblings with childhood-onset polyneuropathy and accompanying erythromelalgia that is exacerbated by infection." (PMID 39352636, 2025). "More recently, two NMNAT2 missense variants (V98M and R232Q, which confer partial and complete LOF respectively in laboratory assays), were identified in two brothers with a progressive neuropathy syndrome, who also have erythromelalgia that worsens with infection." (PMID 39352636, 2025).
glioma (2 papers, 2021 to 2023). A benign or malignant brain and spinal cord tumor that arises from glial cells (astrocytes, oligodendrocytes, ependymal cells). "However, to the best of our knowledge, BST1 and NMNAT2 were found to be closely associated with glioma for the first time." (PMID 36778644, 2023). "We determined NMNAT1 and NMNAT2 protein levels in human glioma cells and normal astroglia cells (SVG p12)." (PMID 34919052, 2021). "Compared to SVG p12 cells, NMNAT1 and NMNAT2 are increased in both glioma cells T98G and U87MG." (PMID 34919052, 2021). "Therefore, it is speculated that NMNAT2 may also act on glioma through NAD+ metabolism." (PMID 36778644, 2023). "We next examined the function of NMNAT in human glioma cell proliferation, specifically human NMNAT1 (nuclear) and NMNAT2 (cytoplasmic)." (PMID 34919052, 2021). "Most importantly, it proved that CD38, NMNAT2, PARP9, and BST1 might be important prognostic molecular markers and potential therapeutic targets for glioma patients." (PMID 36778644, 2023). "The four genes, PARP9, BST1, NMNAT2, and CD38, might be important molecular biomarkers and therapeutic targets for glioma patients." (PMID 36778644, 2023).
Insulin resistance (2 papers, 2019 to 2025). Increased resistance towards insulin, that is, diminished effectiveness of insulin in reducing blood glucose levels. "Vitamin K epoxide reductase complex, subunit 1-like 1 (VKORC1L1), BTD, GPC1, MOCOS, GPC5, AKR1C4, and NMNAT2 are novel biomarkers for the development of insulin resistance." (PMID 30678306, 2019).
lung adenocarcinoma (2 papers, 2020 to 2024). A carcinoma that arises from the lung and is characterized by the presence of malignant glandular epithelial cells. "Similar to the DGUOK, high levels of NMNAT2 were associated with the poor overall survival of patients with lung adenocarcinoma." (PMID 33392072, 2020). "Lung adenocarcinoma shows high expression levels of NMNAT2, and the expression of this gene in this type of cancer was found to negatively correlate with patient survival in two different databases." (PMID 38396769, 2024). "NMNAT2 expression was increased in lung adenocarcinoma and NMNAT2 level was negatively correlated with the overall survival of patients with lung adenocarcinoma." (PMID 33392072, 2020). "We also showed that NMNAT2 was highly expressed in lung adenocarcinoma and negatively correlated with the patient overall survival." (PMID 33392072, 2020). "Since NMNAT2 involved lung adenocarcinoma progression, targeting NMNAT2 may benefit in the treatments of lung adenocarcinoma." (PMID 33392072, 2020). "We found that the DGUOK and the NMNAT2 were dramatically up-regulated in lung adenocarcinoma." (PMID 33392072, 2020). "DGUOK silencing in lung adenocarcinoma cells reduces the NAD+ levels and downregulates NMNAT2 expression (both at the mRNA and at the protein level) through a mechanism that does not depend on mitochondria complex I activity." (PMID 38396769, 2024). "In this study, we found that NMNAT2 mediates NAD+ biogenesis induced by DGUOK and that the NMNAT2 expression negatively correlates with overall survival in the patients with lung adenocarcinoma." (PMID 33392072, 2020). "Our study suggested that DGUOK regulates NAD+ in a NMNAT2 dependent manner and DGUOK-NMNAT2-NAD+ axis could be a potential therapeutic target in lung adenocarcinoma." (PMID 33392072, 2020).
osteosarcoma (2 papers, 2019 to 2024). A usually aggressive malignant bone-forming mesenchymal neoplasm, predominantly affecting adolescents and young adults.
proteinopathies (2 papers, 2016 to 2025). "NMNAT2 mRNA levels correlate positively with cognitive function in older adults but decline after injuries or proteinopathies." (PMID 41241829, 2025). "The dual-function of NMNAT2 makes it a very potent neuronal maintenance factor; it can provide sufficient local NAD to maintain neurons after high frequency neurotransmission and can also act as a chaperone to reduce proteinopathies." (PMID 27254664, 2016).
viral infection (2 papers, 2025). "Moreover, RNA interference-mediated acute genetic loss of Nmnat2 may drive spontaneous degeneration due to the inherent additional cellular stress of this technique (e.g., viral infection) that synergizes with SARM1 activation." (PMID 40496808, 2025). "Interestingly, previous studies have reported that the NAD+ synthesis or consumption genes NAMPT, SIRT1, SIRT2, and CD38 were upregulated during various viral infections, while Nmnat2 was found to decrease following Zika virus infection." (PMID 40006932, 2025). "Based on these findings, we selected five genes—Nampt, Nmnat2, Sirt1, Sirt2, and CD38—that were consistently upregulated in both RD and A549 cells, to evaluate their protein expression levels after viral infection." (PMID 40006932, 2025).
Zika virus infection (2 papers, 2024 to 2025). "Initial studies demonstrated that NAD+ metabolism may be highly dependent on MAPK-mediated nicotinamide mononucleotide adenylyltransferase 2 (NMNAT2) degradation, thereby promoting axon degeneration; this suggests that ZIKV infection alters cellular metabolism via the MAPK-NMNAT2-NAD+ axis." (PMID 37946006, 2024).
agranulocytosis (1 paper, 2020). "Lastly, in another GWAS study, rs41314643 (NMNAT2) was associated with the risk of clozapine-induced agranulocytosis/granulocytopenia." (PMID 31941550, 2020).
Autoimmunity (1 paper, 2021). The occurrence of an immune reaction against the organism's own cells or tissues. "In this study, we directly addressed whether neuronal NMNAT2 overexpression rescues neurodegeneration induced by autoimmunity and inflammation." (PMID 34707482, 2021).
cholangiocarcinoma (1 paper, 2024). A carcinoma that arises from the intrahepatic biliary tree (intrahepatic cholangiocarcinoma) or from the junction, or adjacent to the junction, of the right and left hepatic ducts (hilar cholangiocarcinoma). "Examining NMNAT2 gene alterations in the cBioPortal database revealed that the NMNAT2 gene is also amplified in tumors such as cholangiocarcinoma, invasive breast carcinoma, and hepatocellular carcinoma." (PMID 38396769, 2024).
growth failure (1 paper, 2021). "Homozygous Nmnat2 gene trap mice (Nmnat2gtE/gtE), which express no detectable NMNAT2, die perinatally with nerve growth failure and a hunched posture." (PMID 34910914, 2021).
lung carcinoma (1 paper, 2009). "BICD2, CDA, NMNAT2, SERPINB13, and TOX3 have no specificity to either AC or SCC but to lung cancer." (PMID 19761563, 2009).
meningioma (1 paper, 2020). A generally slow growing tumor attached to the dura mater. "Though there were only four normal samples in GSE43290, the efficacy evaluation results still showed that five genes, including AHCYL2 (AUC = 0.729), FGL2 (AUC = 0.782), ID3 (AUC = 0.926), KCNMA1 (AUC = 0.745), and NMNAT2 (AUC = 0.851), could significantly distinguish meningiomas and normal samples." (PMID 32596316, 2020). "What is more, these genes, excluding ID1, ID3, and NMNAT2, were confirmed to be able to differentiate between the recurrence and nonrecurrence forms of meningioma (P < 0.05)." (PMID 32596316, 2020).
motor peripheral neuropathy (1 paper, 2022). Inflammation or degeneration of the peripheral motor nerves. "The NMNAT2/SARM1 axon degeneration pathway functions in both sensory and motor neurons; yet, curiously, Nmnat2V98M/R232Q mice primarily develop a motor peripheral neuropathy." (PMID 36287209, 2022).
neuroblastoma (1 paper, 2025). Neuroblastoma (NB) is the most common solid, extracranial childhood tumor. "We then moved to analyze modulation of NMNAT2 expression in the Vacor‐sensitive SH‐SY5Y neuroblastoma cell lines." (PMID 40955574, 2025).
ocular hypertensive (1 paper, 2025). "WLDS and Nmnat gene therapy’s preservation of RGC electrical function in ocular hypertensive mice suggests a role for NMNAT2 in maintaining RGC somal viability." (PMID 41397991, 2025).
optic neuritis (1 paper, 2021). Optic neuritis is inflammation of the optic nerve, the nerve that carries the visual signal from the eye to the brain.The conditionmay cause sudden, reduced vision in the affected eye(s). "We therefore tested an Adeno-associated virus (AAV)-mediated gene therapy strategy in the mouse EAE/optic neuritis model and specifically expressed long half-life NMNAT2 mutant (NMNAT2Δex6) in the mouse RGCs in vivo." (PMID 34707482, 2021). "In summary, we established RGC-specific upregulation of NMNAT2, which enabled us to evaluate the autonomous effect of neuronal NMNAT2 modulation on EAE/optic neuritis neuroprotection." (PMID 34707482, 2021). "We therefore investigated whether activation of NMNAT2 can be used as a gene therapy strategy for neuroprotection in EAE/optic neuritis." (PMID 34707482, 2021). "Because axonal Wallerian degeneration is a major component of early axonal pathology in MS, we reasoned that overexpression of NMNAT2 in RGCs might achieve neuroprotection in EAE/optic neuritis." (PMID 34707482, 2021). "To determine whether the neuronal autonomous effect of NMNAT2 provides RGC and ON protection in EAE/optic neuritis, we first confirmed that NMNAT2 can be expressed in mouse RGCs in vivo." (PMID 34707482, 2021). "After confirming the RGC-specific expression of NMNAT2, we investigated its effect on the retina morphology and visual function in mice with EAE/optic neuritis." (PMID 34707482, 2021). "Taken together, the present results showed that NMNAT2 overexpression in RGCs does not achieve neuroprotection or preserve visual function in EAE/optic neuritis." (PMID 34707482, 2021). "Postmortem histological analysis of retina wholemounts and semithin sections of ON confirmed the in vivo results: NMNAT2 activation in RGCs does not provide significant neuroprotection of RGCs in EAE/optic neuritis." (PMID 34707482, 2021).
pancreatic cancers (1 paper, 2024). "In this study, analysis of TCGA database also showed that various tumors, including pancreatic cancers, have frequent gene amplification of NAMPT and NMNAT2." (PMID 38625917, 2024). "Kaplan-Meier analysis showed that overall survival was significantly shorter in pancreatic cancer patients with high NAMPT expression levels, whereas overall survival was not affected by NMNAT2 expression." (PMID 38625917, 2024).
retinal degeneration (1 paper, 2020). Degeneration of the retina. "Since the loss of NMNAT1 induced retinal degeneration, we wished to determine the role of NMNAT2 and 3 in the retinal structure/function." (PMID 33107823, 2020).
schizophrenia (1 paper, 2021). A major psychotic disorder characterized by abnormalities in the perception or expression of reality. "NMNAT2 is important for the maintenance of neurons and is known to be neuroprotective in several models of neurological disorders, while HLA-DRB1 is the most frequently reported genetic association to schizophrenia." (PMID 33892787, 2021).
uterine cancer (1 paper, 2024). Primary or metastatic malignant neoplasm involving the uterine corpus and/or the cervix. "Analysis of TCGA database showed gene amplification of NAMPT and NMNAT2 at relatively high frequency in various types of cancer, including pancreatic, breast, ovarian, and uterine cancers." (PMID 38625917, 2024).